IL27 (interleukin 27)
Diseases named in the same sentence as IL27 in open-access papers (continued):
Sharing a sentence is not in itself a finding about the gene and the disease.
cancer (continued). "Current clinical applications of targeting IL-27 are more advanced in the setting of cancer and focus on blocking immunosuppressive activities." (PMID 38966644, 2024). "A human monoclonal (IgG1) antibody against the IL-27p28 subunit CHS388 (former SRF388), that blocks IL-27/IL-27RA interaction is under consideration for cancer treatment, where a Phase I study has already been shown to be safe in humans." (PMID 38966644, 2024). "We tested the functional consequence of IL-27 treatment on CD27+Ly6C+ γδ T cells in cancer cell line-killing assays." (PMID 38816652, 2024). "We have earlier reported that under the influence of cancer conditioned media mimicking the cancer microenvironment, CVMSCs express a variety of anti-proliferative proteins such as IL-27, MSTN, and TGF-β2, and pro-apoptotic proteins including IFN-α2 and FASLG." (PMID 37298519, 2023). "Despite the need for the development of effective immunotherapies for the treatment of CLL, as well the recently unraveled promise of IL-27 in cancer therapeutics, the role of IL-27 in the development and progression of CLL remained largely unexplored." (PMID 37937211, 2023). "IL-27, a cytokine belonging to the IL-12 family of cytokines, has been identified as a potential cancer vaccine adjuvant." (PMID 35529885, 2022). "Expression of IL27 was significantly correlated with immune regulatory gene expression and immune cell infiltration in pan-cancer." (PMID 36713514, 2022). "The important role of IL-27 in constraining inflammation has prompted the development of antagonist antibodies, one of which is currently being developed as a cancer immunotherapy." (PMID 35579417, 2022). "Our prognostic model identified IL27 as a key gene, and then further analysis on the relationship between IL27 and immune signature was performed in pan-cancer, as IL27 was a significant prognostic cytokine." (PMID 36713514, 2022). "IL-27 can signal in T cells, macrophages, and monocytes while also directly impacting cancer cell death and proliferation." (PMID 35529885, 2022). "In advanced non-small cell lung cancer (NSCLC) patients, IL-27 has also been shown to play a pro-tumorigenic role, where IL-27 induced tolerogenic dendritic cells that helped cancer cells to escape from immune surveillance." (PMID 33418929, 2021). "The combination of IL-27 followed by IL-18 (27→18) successfully reduced cancer cell viability, with significant effects in cell culture and in an immunocompetent mouse model." (PMID 34209203, 2021). "Since HDAC6 was necessary for the metastatic potential enhanced by PSA, we examined the effect of IL-27 on the metastatic potential of cancer cells." (PMID 34234781, 2021). "Incubation of cancer cells with IL-27 results in downregulation of proangiogenic genes, including AKT, angiopoietin, MMP9, VEGF, and laminin, and in upregulation of antiangiogenic genes, such as CXCL9 and CXCL1083." (PMID 34045653, 2021). "Our results showed roles of IL-27 in anaphylaxis and metastatic potential of cancer cells enhanced by PSA." (PMID 34234781, 2021). "Supporting our results, previous studies have identified IL-27 as an NK cell activator by promoting their cell viability and cytolytic activity in several cancer models." (PMID 33014872, 2020). "The role of IL-27 in cancer is still a matter of debate, considering that both pro-inflammatory and anti-inflammatory actions of IL-27 were demonstrated." (PMID 30936876, 2019). "The roles for IL-27 in cancer have been studied in both in vitro and in vivo models and it is important to consider how IL-27 is introduced to the model system given that this cytokine is heterodimeric and the subunits are non-covalently associated in nature." (PMID 31681561, 2019). "We also demonstrated here that IL-15/IL-18/IL-27-stimulated NK cells retained high perforin expression and underwent some target-dependent degranulation and that target cancer cells experienced caspase-dependent apoptosis." (PMID 31277710, 2019).
cancer (continued). "With the limited understanding of IL-30 biology and specifically how it functions within the TME, more research is needed to fully elucidate the interplay between IL-27, IL-30, and IL-35 in cancer progression." (PMID 31681561, 2019). "IL-27 upregulates TLRs in cancer cells and immune cells, resulting in enhanced cellular responsiveness to TLR agonists, supporting the combination of IL-27 and TLR agonists as a potential cancer therapy." (PMID 31681561, 2019). "In in vitro and in vivo models, the use of either recombinant IL-27 or IL-27-transduced cancer cell lines has characterized the role of IL-27 in regulation of the CTL response." (PMID 31681561, 2019). "Soon after its discovery by Pflanz in 2002, IL-27 became a trendy subject in oncology-immunology, scientists started investigating its roles in carcinogenesis, use as a cancer biomarker, and designing novel immune therapies." (PMID 30581461, 2018). "The broad activity of IL-27 on different types of human cancer cells implies IL-27Rα expression in these cells, as was formally demonstrated in different reports." (PMID 28255204, 2017). "Here we will address the dual role of IL-27 in immune regulation and cancer and its functional similarities with IFN-γ." (PMID 28255204, 2017). "IL-27 is a cytokine of the IL-12 family and has shown impressive antitumor effects in different cancer models." (PMID 28255204, 2017). "Here, we will summarize IL-27 biological activities and its functional overlaps with the IFNs and discuss its dual role in tumors in the light of potential applications to cancer immunotherapy." (PMID 28255204, 2017). "Given its broad effects on immune regulation, IL-27 is considered a promising therapeutic target in autoimmune and infectious diseases as well as cancers." (PMID 29021521, 2017). "The IL-27-mediated up-regulation of the APM components prompted us to study the effect of IL-27 on the surface expression of HLA class I molecules on a broader panel of cancer cells." (PMID 27683036, 2016). "To gain more information on IL-27 effects on cancer cells, we used a proteomic approach based on high-resolution mass spectrometry on cell lysates from cytokine-treated or untreated cells, in triplicate independent experiments." (PMID 27683036, 2016). "The present data indicate that IL-27 profoundly modifies the protein expression profile of human cancer cells and modulates a broad set of proteins in a similar fashion as IFN-γ." (PMID 27683036, 2016). "In vitro, IL-27 was ineffective on cancer cell proliferation or apoptosis, but fostered CXCL3/GROγ/MIP2β expression." (PMID 25638163, 2015). "IL-27's ability to modulate angiogenesis-related genes in different cancer cell types, leading to anti-angiogenic effects in vivo, has been documented by us and others." (PMID 25638163, 2015). "The model can be used to examine the effect of injecting IL-27 into the microenvironment of cancer in a mouse, and design strategies for such injections." (PMID 24633175, 2014). "We next extend the model to include therapeutic treatment of cancer in wild type mice by injection of IL-27." (PMID 24633175, 2014). "Recently, IL-27 has been considered a biomarker for a certain infection of cancer." (PMID 40129989, 2025). "Moreover, hypoxia, soluble factors (such as HIF-α, TGF-β, IL-10, and IL-27) and cancer-derived circRNA present in the TME have been shown to induce ICs expression on T cells." (PMID 40607422, 2025). "In the group without T2D, IL-27 was significantly associated with cardiovascular and cancer mortality in the present study." (PMID 39334377, 2024). "Finally, the relationship between IL27, a significant prognostic immune and inflammation cytokine, and immune status was analyzed in pan-cancer." (PMID 36713514, 2022). "Due to the role of IL-27 in the regulation T cell-mediated inflammation, inhibition of IL-27 is currently being explored for its use in the inhibition of aberrant IL-27 signaling in cancer." (PMID 35579417, 2022).
cancer (continued). "However, the use of IL-27 as an adjuvant to improve prophylactic cancer vaccines needs further investigation." (PMID 35529885, 2022). "The relationship between IL27 and immune signature was analyzed in pan-cancer in this research." (PMID 36713514, 2022). "Low IL-27 levels in subjects who benefitted from troriluzole and nivolumab may reflect the dual role of IL-27 in cancer immunotherapy." (PMID 35780243, 2022). "Besides the role of IL-27 in regulating the differentiation of macrophages, IL-27 can also regulate several key surface molecules on cancer cells." (PMID 33418929, 2021). "Since IL-27 is known to upregulate surface HLA Class I expression in different types of human cancer cells, we assessed whether this effect also occurred in MM cells." (PMID 34439164, 2021). "In the pathogenesis of cancer, elevated IL‐6 and IL‐27 could stimulate the activation of JAK1 and JAK2 enzymes, which subsequently mediate tyrosine phosphorylation of STAT3 at Tyr705." (PMID 33277798, 2021). "Thus, targeting hyperactivated IL‐6/IL‐27‐JAK‐STAT3 pathway is beneficial in the treatment of certain cancers." (PMID 33277798, 2021). "We showed that IL-27 shares several effects with IFN-γ in human cancer cells." (PMID 32093058, 2020). "IL27 has been identified as a potentially useful target for anti-cancer clinical applications, probably due to its ability to regulate CD8+ T cells, natural killer cells, macrophages, and other immune checkpoints; our present findings regarding IL27 are consistent with these prior studies." (PMID 32756008, 2020). "IL-27 also enhances NK cell cytotoxicity toward cancer cells." (PMID 31681561, 2019). "However, these apoptotic cancer cells are endocytosed by DCs, which results in IL-27 expression leading to IL-27-dependent Treg activation." (PMID 31681561, 2019). "In vivo studies using cancer cells transduced with an IL-27 expression vector permits continual IL-27 production and ensures that IL-27 is present within the TME; however, the dose and length of exposure becomes more challenging to control in the studied model." (PMID 31681561, 2019). "In addition, we suggest a combination of IL-15, IL-18, and IL-27 in human NK cell culture can lead to increased effectiveness of NK cell-mediated immunotherapeutics against cancers or infectious diseases." (PMID 31277710, 2019). "Although many studies suggested IL-27 administration for cancer immunotherapy, its therapeutic use as an anticancer agent may not be effective and potentially even detrimental (in certain tumors where IL-27 has been associated with a protumor effect)." (PMID 30581461, 2018). "Therefore miRNA-6852 (SX4) is a novel microRNA differentially regulated by IL-27, which exerts anti-cancer effects by inducing G2/M arrest and cellular necrosis by regulating FoxM1." (PMID 29343703, 2018). "In cancer cells, IL-27 can activate apoptosis via several pathways as presented in some reports." (PMID 28732053, 2017). "Nonetheless, given its immune-regulatory functions, the effects of IL-27 on cancer may be dual and protumor effects may also occur." (PMID 28255204, 2017). "Indeed, IL-27 up-regulates multiple components of the HLA class I antigen presentation machinery in human cancer cells, thus facilitating Cytotoxic T Lymphocyte (CTL) recognition." (PMID 29020964, 2017). "From these observations, IL-27 signaling pathway may regulate the suppression program that drives the development of T cell exhaustion in cancer and chronic viral infections." (PMID 28545567, 2017). "IL-27 failed only in a cancer cell line bearing a homozygous deletion in the B2M gene." (PMID 27683036, 2016). "In order to understand the significance and relevance of IL27 signaling in the bone marrow cells to human cancer patients, we analyzed the levels of IL27RA in normal vs. malignant tissue and determined the IL27RA-positive cells in the stroma in correlation to the disease progression." (PMID 27738312, 2016).
cancer (continued). "Our results indicate that IL-27 might inhibit Th17 differentiation in NSCLC patients and better understanding of the regulatory effects of IL-27 on Th17 cells may shed light on potential new targets in cancer prevention and therapy." (PMID 25969628, 2015). "Expression of Nestin was weakened in cancer cells forming SK-MES tumors from IL-27-treated mice." (PMID 25638163, 2015). "The possible role of IL-27 in immune-regulatory networks in cancer is still poorly understood." (PMID 26657115, 2015). "Altogether these findings support the potential use of IL-27 as anti-cancer agent." (PMID 26657115, 2015). "IL-27 similar to other cytokines studied as potential anti-cancer agents, e.g. IL-18 or IL-21, may have a dual role in immune-regulation." (PMID 26657115, 2015). "Our data suggest that IL-27, a cytokine produced by macrophages or DCs, may provide an alternative stimulus for PD-L1 expression, in cancer cells." (PMID 26657115, 2015). "Our present data indicate that also IL-27 has similar activities and suggest that the therapeutic use of IL-27 as anti-cancer agent may have dual effects, in some tumors." (PMID 26657115, 2015). "Indeed, several observations indicate that IL-27 has a dual role in cancer and in immune-regulation and inflammation." (PMID 26657115, 2015). "Data gathered in this study also shows that IL-23/IL-27 ratio may play an important role in cytokine-based immunotherapy against cancer." (PMID 25031487, 2014). "This may explain why these cells only show a significant biological response to IL-27 in vitro in the form of a significant reduction in cell proliferation and a prominent change in the cancer cell angiogenic program." (PMID 24681516, 2014). "In this regards, since IL-27 has much less toxicities compared with IL-12, probably due to much lower ability of IL-27 to produce IFN-γ by NK cells, IL-27 may be an attractive candidate as an antitumor agent applicable to cancer immunotherapy." (PMID 20885915, 2010). "In addition, the observation that IL-27 induces PD-L1 and PD-1 suggests that IL-27 may be an important molecule in controlling cancer-related immune checkpoint mechanisms." (PMID 36245983, 2022). "Several reports indicated that IL-27 may play a dual role in cancer biology and immunotherapy." (PMID 34439164, 2021). "Therefore, it is important to understand IL-27-mediated changes in miRNA profiles in these cell types; further studies may provide new insights into IL-27 immunotherapy for infectious diseases and cancer." (PMID 33525571, 2021). "Indeed, in a previous study, we showed that IL-27, a cytokine produced by macrophages or DCs, may provide an alternative stimulus for PD-L1 expression in different types of human cancer cells." (PMID 34439164, 2021). "Further, these findings may explain the contradictory effects of IL27 observed in cancers." (PMID 34733272, 2021). "We first examined whether IL-27 could affect invasion potential of cancer cells." (PMID 34234781, 2021). "Therefore IL-35 may behave similarly to IL-27 to have divergent roles in cancer progression that may be dependent on cancer type, stage, and TME landscape." (PMID 31681561, 2019). "IL-27 caused, in both cell lines, a significant down-regulation of a series of anti-angiogenesis related genes namely FGFR3, PTGS1 and, particularly, FLT1, which has been reported to be firmly and strongly expressed in hPCa and involved in cancer cell proliferation via autocrine VEGF signaling." (PMID 24681516, 2014). "However, the IL-23/IL-27 ratio may play an important role in cytokine-based immunotherapy against cancer." (PMID 25031487, 2014). "This suggests that IL-27 could play an important role in immunotherapy against human cancer." (PMID 24633175, 2014). "Therefore, IL-27 and the combination of IL-27 and poly(I:C) may be attractive candidates as antitumor agents applicable to cancer immunotherapy." (PMID 24155891, 2013).
cancer (continued). "Thus, IL-27 and the combination of IL-27 and poly(I:C) may be attractive candidates for cancer immunotherapy." (PMID 24155891, 2013). "IL27-independent function of WSX1 and its association with cancer biology is unknown." (PMID 21559505, 2011). "Cancer cells have evolved an innate program to respond to different cytokine stimuli (Ifnγ, IL-27, or IL-1) by upregulating both IDO1 and PD-L1 to promote cancer cell survival." (PMID 37985999, 2023). "IL-27 is known to directly impact both CD4+ and CD8+ T cells and both cell types have a role in promoting cancer vaccine efficacy." (PMID 35529885, 2022). "Specifically, in cancer cells, IDO1 upregulation is mostly dependent on STAT1, and IL-27 regulation of PD-L1 occurs through signal transducer and activator of transcription 3 (STAT3)." (PMID 34944437, 2021). "Our observations are in good agreement with previous findings in cancer cells, showing that particularly the involvement of STAT1 activation is responsible for proteomic remodeling by IL-27." (PMID 33871355, 2021). "Thus, IL-27 might enhance tumorigenic and metastatic potentials of cancer cells." (PMID 34234781, 2021). "In the mock-irradiated cancer microenvironment, there was a significant correlation between CD80 and Flt-1 (r = 0.7857, p = 0.04), and an inverse correlation between CD80 and IL-27 (r = −0.8214, p = 0.03)." (PMID 33540635, 2021). "The ability of IL-27 to increase CTL cytotoxicity while decreasing Treg activity, outlines the potential use of IL-27 in gene-therapy, cancer vaccines, T cell adoptive transfer, or CAR T cell therapies." (PMID 31681561, 2019). "For example, TRAIL, interleukin (IL)-12, IL-27, cytosine deaminase, and oncolytic adenovirus are transduced into MSC to treat cancer." (PMID 31827180, 2019). "Altogether, these data indicate that IL-27 and IFN-γ display a broad overlap of functions in human cancer cells, which are related to STAT1 pathway activation by both cytokines." (PMID 28255204, 2017). "In conclusion, proteomic data indicate that IL-27 shows broadly overlapping functions with IFN-γ, in human cancer cells, most likely in relationship to the common usage of the STAT1 pathway." (PMID 27683036, 2016). "Altogether these data show, for the first time, that IL-27 induces IDO and PD-L1 expression in human EOC cancer cells through activation/phosphorylation of STAT1 or STAT3, respectively." (PMID 26657115, 2015). "To better characterize the role of IL-27 in regulating immune suppressive molecules in cancer, we investigated its ability to induce IDO and PD-L1 in EOC and other cancer cells." (PMID 26657115, 2015). "On this basis and given the fact that IL-27 regulates STAT transcriptional factors (STAT1 and STAT3) that possess opposing activities in cancer, the impact of this cytokine on lung carcinogenesis was investigated." (PMID 24274066, 2013). "Furthermore, we previously found that certain cytokines and transcriptional factors, including IL-6, IL10, IL-27, STAT, and NF-kB, regulate PD-L1 expression in various cancers." (PMID 36757936, 2023). "In addition, expression of IL27 was positively correlated with immune regulatory gene expression and the immune score, stromal score, and ESTIMATE score in pan-cancer." (PMID 36713514, 2022). "As a therapeutic, IL-27 is not reported in the literature to promote the direct killing of cancer cells." (PMID 35200430, 2022). "It seems that IL-27 induces the expression of both IDO and PD-L1 in human cancer cells." (PMID 34944437, 2021). "IL-27, with its diverse influences on immune responses, has not been studied extensively in NMSCs and its roles in cancer initiation, progression, and its probable use in NMSC treatment have yet to be revealed." (PMID 30581461, 2018). "Additionally, IL-12, IL-27, IL-17 and TNF-α regulated PD-L1 expression in inflammatory cells and cancer cells by altering NF-κB, STAT1 and ERK1/2 signaling." (PMID 29690901, 2018).